TIMM44 (translocase of inner mitochondrial membrane 44)
Description:
Essential component of the PAM complex, a complex required for the translocation of transit peptide-containing proteins from the inner membrane into the mitochondrial matrix in an ATP-dependent manner (By similarity). Recruits mitochondrial HSP70 to drive protein translocation into the matrix using ATP as an energy source (By similarity).
Synonyms: TIM44
Tractability: Antibody: UniProt places it where antibodies can reach, with high confidence. PROTAC: ubiquitination databases record sites on it; its protein half-life has been measured.
Gene: Protein-coding gene on chromosome 19 (7,926,718 to 7,943,773, reverse strand). Ensembl gene ENSG00000104980.
Subcellular location: Mitochondrion inner membrane; Mitochondrion matrix
Subcellular location (Human Protein Atlas): Mitochondria
Pathways (Reactome):
Protein localization: Mitochondrial protein import
Gene Ontology:
Molecular function: protein binding; protein-folding chaperone binding; protein-macromolecule adaptor activity
Biological process: intracellular protein transport; protein import into mitochondrial matrix
Cellular component: mitochondrial inner membrane; mitochondrial matrix; mitochondrion; TIM23 mitochondrial import inner membrane translocase complex; PAM complex, Tim23 associated import motor
Genetic constraint (gnomAD): Loss-of-function variants: 37 observed, 64.24 expected, observed/expected ratio (o/e) 0.58, 90% interval 0.44 to 0.76. The upper end of that interval is the gene's LOEUF score, 0.76, which puts it in group 3 of 6, group 1 being the genes least tolerant of losing a copy. Missense variants: 573 observed, 623.78 expected, observed/expected ratio (o/e) 0.92, 90% interval 0.86 to 0.98. Synonymous variants: 239 observed, 249.37 expected, observed/expected ratio (o/e) 0.96, 90% interval 0.86 to 1.07.
Homologues: Orthologues: chimpanzee TIMM44 (99% identical), macaque TIMM44 (98% identical), dog TIMM44 (93% identical), rabbit TIMM44 (92% identical), guinea pig TIMM44 (91% identical), mouse Timm44 (90% identical), rat Timm44 (89% identical), pig TIMM44 (85% identical), zebrafish timm44 (75% identical), tropical clawed frog timm44 (68% identical), Drosophila melanogaster CG11779 (48% identical), Caenorhabditis elegans tin-44 (40% identical).
Diseases named in the same sentence as TIMM44 in open-access papers:
TIMM44 is named in the same sentence as 13 diseases in open-access papers, as found by Europe PMC text mining. Sharing a sentence is not in itself a finding about the gene and the disease. The quoted sentences say what the papers report.
glioma (5 papers, 2022 to 2024). A benign or malignant brain and spinal cord tumor that arises from glial cells (astrocytes, oligodendrocytes, ependymal cells). "Therefore, TIMM44 downregulation in YME1L-deficient glioma cells should be caused by shutdown of GATA3-dependent TIMM44 transcriptional machinery following mitochondrial stress." (PMID 36438483, 2022). "In glioma cells and endothelial cells, TIMM44 shRNA or KO resulted in mitochondrial functional impairment, inhibiting glioma cell growth and angiogenesis." (PMID 38467612, 2024). "TIMM44 expression is elevated in human glioma, whereas TIMM44 silencing or KO potently suppressed glioma cell growth in vitro and in vivo." (PMID 37147302, 2023). "The same group further reported that TIMM44, another mitochondrial protein, promoted glioma cell growth possibly by increasing YME1L transcription and expression." (PMID 37063426, 2023). "To P2 and P3 primary glioma cells and established cell lines (A172 and U251), the TIMM44-expressing lentivirus was added, and stable cells were formed (“OE-TIMM44”)." (PMID 36438483, 2022). "Bioinformatics results and local human glioma tissue data confirmed that TIMM44 mRNA and protein expression is upregulated in glioma." (PMID 36438483, 2022). "In patient-derived primary glioma cells and immortalized cell lines, TIMM44 shRNA or KO (by CRISPR/Cas9 method) potently inhibited cell viability, proliferation and migration." (PMID 36438483, 2022). "As shown, in P1 glioma cells TIMM44 shRNA or KO induced conversion of JC-1 aggregates (in red fluorescence) to the JC-1 green monomers, causing mitochondrial depolarization." (PMID 36438483, 2022). "We found that overexpressed TIMM44 is essential for maintaining mitochondrial functions in glioma cells." (PMID 36438483, 2022). "Significantly, YME1L shRNA-induced anti-glioma cell activity was ameliorated after restoring TIMM44 expression using the TIMM44-expressing construct." (PMID 36438483, 2022). "The viability of the primary and established glioma cells was decreased following TIMM44 silencing, which also exerted anti-proliferative activity and hindered in vitro migration of the glioma cells." (PMID 36438483, 2022). "The applied shRNAs and KO construct resulted in TIMM44 protein depletion as well in P1 glioma cells." (PMID 36438483, 2022). "Bioinformatics studies and results from the local high-grade glioma tissues showed that TIMM44 mRNA and protein levels are elevated in glioma, correlating with poor overall survival." (PMID 36438483, 2022). "We found that the average mitochondrial length was similar between control glioma cells and TIMM44-silenced/KO glioma cells." (PMID 36438483, 2022). "On the contrast, DCF-DA intensity was decreased, suggesting decreased ROS contents following TIMM44 overexpression in primary glioma cells." (PMID 36438483, 2022). "Western blotting data of four representative patients, Patient-1 to Patient-4, confirmed TIMM44 protein upregulation in glioma tissues." (PMID 36438483, 2022). "Conversely, TIMM44 overexpression increased cellular ATP contents and alleviated oxidative injury in primary glioma cells." (PMID 36438483, 2022). "TIMM44 upregulation in glioma is possibly due to increased TIMM44 transcriptional machinery by the transcription factor GATA3 in a YME1L (YME1 Like 1 ATPase)-dependent manner." (PMID 36438483, 2022). "TIMM44 overexpression potentiated cell proliferation (increasing EdU-positive nuclei percentage) and migration in the glioma cells." (PMID 36438483, 2022). "Combining all 16 pairs of blotting data showed that TIMM44 protein upregulation in glioma tissues was significant (P < 0.05 vs. “N” tissues)." (PMID 36438483, 2022). "TIMM44 expression in primary human glioma cells was decreased following YME1L silencing or KO, but was elevated after ectopic YME1L overexpression." (PMID 36438483, 2022). "In both TCGA and Chinese Glioma Genome Atlas (CGGA), patients with high TIMM44 expression in gliomas have worse prognosis and lower survival." (PMID 36438483, 2022).
glioma (continued). "mRNA expression of TIMM44-dependent mitochondrial genes, including Opa1, Mfn1 and Mfn225, were dramatically decreased with TIMM44 silencing or KO in P1 glioma cells." (PMID 36438483, 2022). "In OE-TIMM44 P1 glioma cells TIMM44 mRNA and protein levels were indeed dramatically increased and TIMM23 expression was unchanged." (PMID 36438483, 2022). "Mitochondrial TIMM44 upregulation was also detected in patient-derived primary glioma cells and immortalized cell line." (PMID 36438483, 2022). "YME1L silencing or KO resulted in reduction of TIMM44-dependent mitochondrial genes, including Opa1, Mfn1 and Mfn2, in P1 glioma cells." (PMID 36438483, 2022). "As shown YME1L shRNA and KO resulted in significant TIMM44 mRNA and protein downregulation in P1 glioma cells." (PMID 36438483, 2022). "shRNA-induced silencing of GATA3 significantly decreased TIMM44 mRNA and protein expression in P1 glioma cells, and YME1L expression was unchanged." (PMID 36438483, 2022). "Supporting increased lipid peroxidation, we found that the TBAR activity was augmented in TIMM44-silenced or TIMM44-KO P1 glioma cells." (PMID 36438483, 2022). "The results of the present study supported that the mitochondrial protein TIMM44 is an important cancer-promoting molecular for glioma progression." (PMID 36438483, 2022). "TIMM44 depletion, ATP reduction, oxidative injury and apoptosis were detected in TIMM44 shRNA AAV-injected glioma xenografts." (PMID 36438483, 2022). "Opa1, Mfn1 and Mfn2, TIMM44-dependent mitochondrial genes, were increased in TIMM44-overexpressed P1 glioma cells." (PMID 36438483, 2022). "Results showed that TIMM44 mRNA expression in the primary and established glioma cells was higher than that in the primary human astrocytes (“Astrocytes1/2”, derived from two patients)." (PMID 36438483, 2022). "In primary and established glioma cells, TIMM44 depletion, using the lentiviral shRNA strategy or the CRISPR/Cas9 knockout (KO) method, robustly inhibited cell viability, proliferation and migration." (PMID 36438483, 2022). "TIMM44 shRNA (by shTIMM44-seq1) or KO robustly inhibited the import of Su9-DHFR fusion protein into the mitochondria of P1 glioma cells, and about 60-70% reduction of mitochondrial protein import was achieved with TIMM44 silencing/KO." (PMID 36438483, 2022). "As compared to control glioma cells with the lentiviral scramble shRNA (lv-shC), TIMM44 expression was robustly decreased in shTIMM44-seq1-expressing glioma cells." (PMID 36438483, 2022). "In TIMM44-silenced or TIMM44-KO P1 glioma cells, TUNEL-positive nuclei percentage was significantly increased." (PMID 36438483, 2022). "Ectopic overexpression of TIMM44 promoted P1 glioma cell proliferation, which was evidenced by the increased EdU-positive nuclei percentage." (PMID 36438483, 2022). "Next, the lentiviral TIMM44-expressing construct (“OE-TIMM44”) was transduced to the lv-shYME1L P1 glioma cells and restored TIMM44 expression." (PMID 36438483, 2022). "In addition, the same group reported that YME1L expression driven by the mitochondrial protein TIMM44 (translocase of inner mitochondrial membrane 44) promoted glioma cell growth." (PMID 38890304, 2024). "Mitochondrial dysfunction was observed in TIMM44-depleted glioma cells." (PMID 37147302, 2023). "Moreover, GATA3 binding to the TIMM44 promoter was significantly increased in both human glioma tissues and difference glioma cells." (PMID 36438483, 2022). "Upregulation of TIMM44 in glioma could be due to increased TIMM44 transcriptional machinery through GATA3." (PMID 36438483, 2022). "Moreover, TIMM44 shRNA or KO largely suppressed P1 glioma cell in vitro migration and invasion, tested by “Transwell” and “Matrigel Transwell” assays, respectively." (PMID 36438483, 2022). "As shown TIMM44 mRNA levels were dramatically decreased in shTIMM44 and ko-TIMM44 P1 glioma cells." (PMID 36438483, 2022).
glioma (continued). "We therefore analyzed whether TIMM44 depletion could result in mitochondrial dysfunctions in human glioma cells." (PMID 36438483, 2022). "TIMM44 overexpression in glioma correlated with poor overall survival of the patients." (PMID 36438483, 2022). "In TIMM44-silenced P1 glioma xenograft tissues, ATP contents were significantly decreased." (PMID 36438483, 2022). "Conversely, ectopic overexpression of TIMM44 augmented glioma cell proliferation and migration." (PMID 36438483, 2022). "We therefore explored the transcriptional mechanism of TIMM44 expression in glioma cells." (PMID 36438483, 2022). "Moreover, the intracranial growth of TIMM44 KO glioma cells in the mouse brain was largely inhibited." (PMID 36438483, 2022). "Thus, TIMM44-silencing-induced anti-glioma cell activity was possibly through disrupting mitochondrial functions." (PMID 36438483, 2022). "We here will show that TIMM44 overexpression exerts significant pro-tumorigenic activity in glioma." (PMID 36438483, 2022). "Therefore, in line with the in vitro findings, ATP reduction, oxidative injury and apoptosis were detected in TIMM44-silenced subcutaneous P1 glioma xenografts." (PMID 36438483, 2022). "At last we tested the potential effect of TIMM44 on glioma cell growth in vivo." (PMID 36438483, 2022). "TIMM44 shRNA also increased the number of TUNEL-positive nuclei in the glioma cells." (PMID 36438483, 2022). "TIMM44 shRNA or KO significantly decreased CCK-8 viability in P1 primary glioma cells." (PMID 36438483, 2022). "Moreover, the growth of intracranial glioma xenografts in nude mice was largely inhibited after TIMM44 KO." (PMID 36438483, 2022). "Importantly, YME1L shRNA-induced decrease of GATA3-TIMM44 promoter binding and TIMM44 downregulation were largely attenuated by exogenously adding ATP in P1 glioma cells." (PMID 36438483, 2022). "Thus far, we found that genetic depletion of TIMM44 inhibited cell proliferation and migration, disrupted mitochondrial functions and induced apoptosis in primary and established glioma cells." (PMID 36438483, 2022). "Moreover, the mitochondrial complex I activity and the cellular ATP contents were significantly decreased following TIMM44 silencing or depletion in P1 glioma cells." (PMID 36438483, 2022). "The cellular ATP contents were augmented in the TIMM44-overexpressed glioma cells." (PMID 36438483, 2022). "In the present study, we found that YME1L could be an important upstream protein for TIMM44 in human glioma cells." (PMID 36438483, 2022). "We therefore tested whether ectopic overexpression of TIMM44 could exert pro-glioma cell activity." (PMID 36438483, 2022). "Thus, mitochondria-localized TIMM44 is upregulated in human glioma tissues." (PMID 36438483, 2022). "Together, overexpressed TIMM44 could be a novel and promising therapeutic target of human glioma." (PMID 36438483, 2022). "Overexpressed TIMM44 could be a novel and promising therapeutic target of human glioma." (PMID 36438483, 2022). "Similar to our results in P1 glioma cells, we found that TIMM44 shRNA decreased mitochondrial complex I activity and ATP contents, while increasing the ROS levels (CellROX intensity increase) in P2/ P3 primary glioma cells and established lines (A172 and U251)." (PMID 36438483, 2022). "Notably, the mitochondrial TIMM44 expression was higher in the glioma tissues." (PMID 36438483, 2022). "Thus, TIMM44 KO largely inhibited intracranial P1 glioma xenograft growth in mouse brain." (PMID 36438483, 2022). "Therefore, YME1L promoted GATA3-dependent TIMM44 transcription in glioma cells." (PMID 36438483, 2022). "We found that TIMM44 mRNA and protein as well as the YME1L protein levels were significantly increased in OE-YME1L glioma cells, whereas TIMM23 mRNA was unchanged." (PMID 36438483, 2022). "ATP also partially restored TIMM44 mRNA and protein expression in YME1L-silenced glioma cells." (PMID 36438483, 2022).
glioma (continued). "Moreover, in human glioma tissues of four representative patients, GATA3 binding to the TIMM44 promoter was significantly higher than that in the matched surrounding normal brain tissues." (PMID 36438483, 2022). "TIMM44 expression and potential functions in glioma have not been examined thus far." (PMID 36438483, 2022). "Moreover, overexpression of YME1L, by the lentiviral YME1L-expressing construct (“+OE-YME1L”), failed to restore TIMM44 mRNA expression in GATA3-silenced P1 glioma cells." (PMID 36438483, 2022). "As compared to the vector control cells (“Vec”), TIMM44 mRNA, but not TIMM23 mRNA, was increased in OE-TIMM44 glioma cells." (PMID 36438483, 2022).
breast carcinoma (4 papers, 2006 to 2022). "For instance, previous studies discovered that TIMM44 was proposed to be in association with susceptibility to breast cancer." (PMID 35501914, 2022). "Furthermore, an intragenic CpG island in TIMM44 has been found to be hypomethylated in aggressive serous ovarian cancers, and its expression is positively associated with recurrence after chemotherapy in breast cancer patients." (PMID 26798410, 2016). "In this context, we developed a new Myc-based Mito-Signature consisting of 3 mitochondrial genes (HSPD1; COX5B; TIMM44) for effectively predicting tumor recurrence (HR=4.69; p=2.4e-08) and distant metastasis (HR=4.94; p=2.8e-07), in ER(+) in breast cancer patients." (PMID 29080556, 2017).
ovarian carcinoma (3 papers, 2022 to 2024). A malignant neoplasm originating from the surface ovarian epithelium. "It has been reported that ELAVL1 interacts with TIMM44 mRNA to regulate its stability in ovarian cancer." (PMID 38394156, 2024). "TIMM44 silencing, however, suppressed ovarian cancer cell growth." (PMID 38467612, 2024). "Conversely, siRNA-induced silencing of TIMM44 inhibited ovarian cancer cell growth." (PMID 36438483, 2022).